KRAS (KRas proto-oncogene, GTPase)
Diseases named in the same sentence as KRAS in open-access papers (continued):
Sharing a sentence is not in itself a finding about the gene and the disease.
pancreatic cancer (continued). "In this study, we first DEGs and DMGs in normal samples versus tumor samples without KRAS wild-type based on expression profiling data of pancreatic cancer, and performed functional analysis." (PMID 36969862, 2023). "SNAIL-related phenotypes displayed remarkable tissue- and genetic context-dependencies, ranging from protective effects as observed in KRAS- or WNT-driven intestinal cancers, to dramatic acceleration of tumorigenesis, as shown in KRAS-induced pancreatic cancer." (PMID 36882420, 2023). "However, in our previous studies, we showed that longitudinal monitoring of KRAS-mutated ctDNA could help identify tumor dynamics in various treatments and revealed a significant correlation between KRAS-mutated ctDNA and CA19-9 levels in pancreatic cancer patients." (PMID 36959222, 2023). "To assess the efficacy of TUS-007 in pancreatic cancer, for which the development of an effective molecular targeted drug has thus far been unsuccessful, we assayed apoptosis and antitumor effects on SW1990 human pancreatic cancer cells (homozygous KRAS G12D)." (PMID 37513471, 2023). "To formally assess the role of GSL metabolism in KRAS oncogenesis, we treated multiple KRAS mutant pancreatic cancer cell lines and a non-transformed pancreatic epithelial cell strain with a UGCG inhibitor." (PMID 36709325, 2023). "Human KRASG12D expression was detected in all six analyzed pancreatic tumors through Q-PCR experiments with mutant KRAS specific primer pairs, but not in DIC control pig without AAV6-PKL injection." (PMID 36650523, 2023). "Consistent with previous reports regarding native albumin, transient KRASG12D overexpression in KRAS wt BxPC-3 cells and inducible KRASG12D expression in tumor cells derived from a genetically engineered mouse model of pancreatic cancer, both enhanced nab-PTX uptake by ≥8-fold." (PMID 35154489, 2022). "In addition, a series of experiments should be performed to investigate the regulatory mechanisms between RAB7A and the pancreatic cancer-related (e.g. MAPK, KRAS, PPAR) pathways screened by GSEA." (PMID 36261459, 2022). "Detection of KRAS does not currently have a role in screening or diagnosis of pancreatic cancer due to difficulty standardizing sampling, transportation, extraction and detection." (PMID 36231137, 2022). "Lnc01420 is upregulated in pancreatic cancer and facilitates pancreatic cancer cell proliferation, metastasis and EMT, and lnc01420 can act as a sponge of miR-494-3p to relieve the inhibition of MYC expression and promotes KRAS gene transcription through the lnc01420/miR-494-3p/MYC regulatory axis." (PMID 35819532, 2022). "The pathways with differences between mutant and nonmutant KRAS samples in Cluster 1 included taurine and hypotaurine metabolism, regulation of autophagy, pancreatic cancer, etc.." (PMID 35340619, 2022). "TMPyP4 (25 μM) and 317605 (1 μM) were examined in a luciferase system that contained either no promoter (EV) or the full length KRAS promoter (KRAS/FL), as well as in pancreatic cancer cell lines that harbored mutant KRASG12D proteins—Panc1 and AsPc1." (PMID 36011352, 2022). "This may be due to the fact that KRAS-G12D patients have a higher TNM stage and more patients lose the chance of surgery when pancreatic cancer is diagnosed, resulting in a decrease in the proportion of KRAS-G12D patients among surgical patients." (PMID 36582783, 2022). "Similar results have also been reported when autophagy inhibitors are combined with ERK1/2 inhibitors (ERKi) in patient-derived pancreatic cancer xenograft models and when used in triple combination with the BRAF and CRAF (also known as RAF1) kinase inhibitors in KRAS-mutant cell lines." (PMID 35147163, 2022). "It was noted that MYEOV could serve as a ceRNA by producing molecular sponging effects on hsa-miR-103a-3p and hsa-miR-107, thus affecting the role of GPRC5A, SERPINB5, EGFR, KRAS, EIF4G2, and PDCD4 on pancreatic cancer progression." (PMID 36358856, 2022).
pancreatic cancer (continued). "The combination of KRAS inhibitors with downstream pathway inhibitors is less commonly reported, and the combined targeting of the MAPK-ERK and PI3K-AKT-mTOR pathways was ineffective in pancreatic cancer models." (PMID 36291766, 2022). "Wnt/β-Catenin, KRAS, EGFR, as well as downstream cellular pathways like MMP and VEGF were found to be downregulated after electrical pulses were applied to pancreatic cancer, and then cancer biology, including proliferation, cell death, invasion, and metastasis, all changed." (PMID 36081554, 2022). "In addition, the PH domain of CNKSR1 combines with mut‐KRAS to inhibit the growth of mut‐KRA cells, which can treat a variety of cancers, such as pancreatic cancer." (PMID 34541834, 2022). "Drug combinations comprising KRAS G12C inhibitors and the FAK inhibitor IN10018 showed promising synergistic effects against diverse cancer cells and multiple cancer models, including NSCLC, CRC, and pancreatic cancer." (PMID 34151545, 2021). "Remarkably, the presence of SGs was observed in mutant KRAS pancreatic cancer cells as opposed to normal cells." (PMID 34604242, 2021). "Following an extended latency, a subset of quiescent pancreatic cancer cells can emerge from dormancy and lead to cancer relapse without re-expression of oncogenic KRAS." (PMID 34491463, 2021). "As reported, growth of KRAS mutant pancreatic cancer cells with targeted inactivation of PIK3CA, a parallel branch of the KRAS signaling pathway, is also inhibited in syngeneic wild-type mice but not in nude mice due to the upregulation of MHC class I expression." (PMID 33674596, 2021). "Combinations being explored include cetuximab plus MRTX849, pembrolizumab, and afatinib in the treatment of KRAS G12C-mutant pancreatic cancer (NCT03785249), as well as cetuximab plus trastuzumab and SNK01 for the treatment of advanced, EGFR-positive pancreatic cancer (NCT04464967)." (PMID 33546207, 2021). "This review provides a brief overview of preclinical and clinical studies focusing on novel therapeutic options concerning specific KRAS, CDK4/6 inhibitors, and combination of immune checkpoint inhibitors with chemo or molecular targeted agents for the treatment of pancreatic cancer." (PMID 34440587, 2021). "Here, the authors show that, in established KRAS-driven pancreatic cancer, KRAS-ablation does not affect intrinsic tumorigenic capacity but elicits antitumor immune response, highlighting the importance of KRAS-driven immune suppression in tumor maintenance." (PMID 33674596, 2021). "Concordantly, ORP5/ORP8 knockdown effectively reduced the number of colonies of the mutant KRAS-dependent pancreatic cancer cells without affecting the cancer cells independent of mutant KRAS." (PMID 34680072, 2021). "Another oncogene, KRas, under nutrient stressed condition, scavenges extracellular proteins to produce glutamine and other amino acids to fuel the tricarboxylic acid (TCA) cycle for survival and growth in pancreatic cancer." (PMID 33968983, 2021). "Therefore, neratinib can coordinately suppress the functions of both mutant KRAS and YAP to kill pancreatic cancer cells." (PMID 33408779, 2021). "KRAS G12R mutations are highly unique for pancreas cancer as they are exceedingly rare, or non-existent, in other cancers (1% in thyroid cancers, <2% in NSCLC, <2% in colon cancers of all KRAS mutant cancers)." (PMID 33405090, 2021).
pancreatic cancer (continued). "In order to test the system, authors used pancreatic cancer cell lines PANC-1 (KRAS G12D), MiaPaCa2 (KRAS G12C) and normal pancreatic ductal epithelial cells H6c7." (PMID 34781949, 2021). "KRas-induced activation of ERK, the main effector of the MAPK-ERK pathway, is thought to be responsible for a host of tumorigenic properties including tumor cell chemoresistance, invasion of pancreatic tumors, and the proliferation of pancreatic tumor cells." (PMID 34680208, 2021). "Here, we show that in an established model of KRAS-driven pancreatic cancer KRAS ablation does not affect intrinsic tumorigenic capacity, but elicits antitumor immune response." (PMID 33674596, 2021). "Epidermal growth factor receptor (EGFR) inhibition has shown promise in clinical trials of unselected patients with advanced pancreatic cancer, but has not been prospectively tested in KRAS wild-type patients." (PMID 34956889, 2021). "In pancreatic cancer, several reports indicate that epidermal growth factor receptor (EGFR) signaling remains active and essential for tumor development despite downstream KRAS activation." (PMID 34070180, 2021). "It is noteworthy that transcription factors, such as ETS2, JUN, and ELK1, were upregulated in the KRAS mutated CRC, but not in lung and pancreatic cancers." (PMID 33982211, 2021). "This suggests that inherent resistance to toceranib through KRAS mediated pathways should not impact response to toceranib in dogs with the more common acinar pancreatic carcinoma." (PMID 34380474, 2021). "Moreover, inhibiting KRas/calmodulin interaction by stimulating PKC-mediated Ser181 phosphorylation of KRas, using the atypical PKC activator prostatin, suppressed tumourigenesis in KRas mutant pancreatic cancer cells as a result of increased CaMKII activity." (PMID 32456244, 2020). "Finally, we were able to assess the role of mutant KRAS testing for distinguishing between PDAC and benign or pre-malignant pancreatic tumours." (PMID 32825312, 2020). "Experimental models have demonstrated the importance of EGFR activation in KRAS-mutant pancreatic cancer, indicating that RAS/MAPK pathway activation is not sufficient to drive pancreatic tumorigenesis." (PMID 32698506, 2020). "Besides inhibiting SIRT1 and PARP1, NAM has shown to inhibit the oncogenic KRAS/AKT pathway in skin and pancreatic cancers, modulate the expression of Myc oncogene in bladder cancer, and suppress IGF-1 in HCC." (PMID 32245130, 2020). "TAZ also was found to promote the metastasis of aggressive patient-derived breast cancer cell lines and, in pancreatic cancer, increased YAP could replace dependence on KRAS activity." (PMID 31772328, 2020). "In pancreatic cancer, NAM suppressed proliferation, cell cycle progression, invasion, and enhanced apoptosis in vitro by down-regulating SIRT1, KRAS (Kirsten Rat Sarcoma), and p-AKT (phosphated protein kinase B), while it exhibited an analogous effect when administered in combination with valproate." (PMID 32245130, 2020). "Future directions could investigate REST in maintaining acinar cell organization during KRAS-driven ADM, which is believed to be an initial event towards pancreatic cancer development." (PMID 32080178, 2020).
pancreatic cancer (continued). "We identified a new regulatory pathway, which is activated in high resistant pancreatic tumor cells, carrying oncogenic KRAS, under gemcitabine treatment but not in sensitive cells to chemotherapy." (PMID 32655498, 2020). "It was discovered in the inducible oncogenic KRAS (Kirsten Rat Sarcoma) mouse model (Ptf1-Cre; Rosa26-rtTa; TetO-KrasG12D) in which pancreatic tumor cells regulate PSCs non-cell-autonomously by secreting factors including SHH protein." (PMID 33333727, 2020). "In addition to the regulation of glycolysis, mutant KRAS signaling stimulates mitochondrial translocation of phosphoglycerate kinase 1 (PGK1), leading to phosphorylated PDHK1 and restricted OXPHOS in pancreatic cancer cells." (PMID 32122374, 2020). "Indeed, AurkA is regulated by KRAS via the MAPK signalling pathway, and, consequently, AurkA is ectopically expressed in pancreatic cancer and KRAS knockdown in PDAC cell lines leads to depletion of AurkA and cilia formation." (PMID 32571902, 2020). "Because ERK lies downstream of KRAS, EGFR cannot induce permanent inhibition in pancreatic cancer, but MEK1/2 inhibitors, which target downstream of KRAS and upstream of ERK, have been approved by the FDA for BRAF mutated melanoma and are being tested in many other cancers." (PMID 30921351, 2019). "In support of this notion, oncogenic KRAS can modulate ADAM17‐induced shedding of EGFR family ligands during colorectal and pancreatic cancers, and genetic targeting of ADAM17 in mouse models for these cancers suppresses tumorigenesis by abrogating EGFR family ligand production." (PMID 30833304, 2019). "The depletion of PRKN also enhanced pancreatic tumorigenesis in KRAS-driven engineered mouse models based on its role in mediating the degradation of mitochondrial iron importers, implying that PRKN can be a potential target for pancreatic cancer therapy." (PMID 31921812, 2019). "Recent studies have also shown that oncogenic KRAS signaling activates NRF2, which is a key redox regulator important for cellular glutathione biosynthesis and plays a critical role in pancreatic cancer cell transformation, survival, proliferation, and metabolism." (PMID 30819189, 2019). "For example, in pancreatic cancer cells, oncogenic KRAS increases the flux of glucose carbon through the non-oxidative PPP to favor nucleotide biosynthesis, without altering flux of glucose carbon to the oxidative PPP (ox-PPP)." (PMID 31288436, 2019). "Interestingly, the results of the two studies seem to be consistent: 6 genes are shared within the first top 20 ranked genes, and in particular, KRAS and MAPK9 are both elements of the pancreatic cancer pathways." (PMID 31652275, 2019). "Early evidence suggested that not all KRAS-mutant tumor cells are dependent on KRAS, and that some KRAS-mutant cancer cells, including lung and pancreatic cancer cells, can survive in the absence of the KRAS oncogene." (PMID 31612108, 2019). "Treatment with LIF antibody had the same effects on activation of Hippo-signaling pathway in human pancreatic cancer cells without altering their KRAS expression and ERK activity." (PMID 31296870, 2019). "Furthermore, inhibition of MEK, but not AKT, by small molecules downregulated the expression of LIF in human pancreatic cancer cell line Panc1.0, suggesting that the MEK/ERK signaling pathway is essential for regulation of LIF expression by KRAS." (PMID 31296870, 2019). "Furthermore, we found that the loss of TBK1 function resulted in reduced invasion, migration, and tumor growth, and reduced metastatic events in preclinical models of mutant KRAS PDAC, indicating that TBK1 actively contributes to pancreatic cancer progression." (PMID 31681587, 2019).
pancreatic cancer (continued). "Besides, recent data underpin a concerted action of mutant KRAS with CDK5 and its activators to intensify malignant progression, migration, and invasion of pancreatic cancer cells." (PMID 30340359, 2018). "Although KRAS mutations are one of the major driver mutations in PDA, KRAS mutation alone is not sufficient to induce invasive pancreatic cancer in mice model." (PMID 29670173, 2018). "In addition to tumorigenesis, glutamate also plays a role in increasing pancreatic cancer cell invasion and migration via AMPA receptor activation and KRAS-MAPK signaling." (PMID 30109143, 2018). "The present study was designed to examine MALAT1 expression and function in pancreatic cancer, to determine whether MALAT1 is a target of miR-217 and to elucidate the interaction between MALAT1 and KRAS." (PMID 28701723, 2017). "However, we recently performed a similar experiment where we inhibited KRAS and the anti-apoptotic genes BCLXL, FLIP, MCL1L, SURVIVIN and XIAP in a panel of murine and human pancreatic cancer cell lines, including the ones that we employed in the current work." (PMID 28415695, 2017). "Although our study represents only three cell lines, the important effect of KRAS G12D or G12C mutations and protein expression on sensitivity to MEK inhibitors and their combinations were never observed before in case of pancreatic cancers." (PMID 28957417, 2017). "Consistent with our observation that KRAS protein expression levels decreased after MALAT1 knockdown was our observation that MALAT1 knockdown also downregulated the MAPK signalling pathway, which is constitutively activated in pancreatic tumours." (PMID 28701723, 2017). "In this study, the authors demonstrate that KRAS is dispensable in a subset of pancreatic cancer and that PI3K signalling may have an important role in mediating tumor growth following KRAS inhibition." (PMID 29061961, 2017). "In order to test the sensitivity of dPCR in mutation detection, we performed a serial dilution experiment using mutant KRAS DNA extracted from the pancreas cancer cell line HPAF-II (G12D; GGT -> GAT) and WT KRAS DNA extracted from the T lymphocyte cell line, Jurkat." (PMID 28125707, 2017). "Furthermore, the activated KRAS(G12D), upstream of ERK1/2 has been shown to reduce E-cadherin expression, and in turn increase invasive and migratory properties of pancreatic cancer cells." (PMID 29262609, 2017). "This is unlikely to be the case given that most pancreatic cancers are KRAS-mutant and both our analysis and a previous publication indicate that the cells used are KRAS-wild type." (PMID 27782819, 2016). "Hence, our data provide a new lncRNA-mediated regulatory mechanism for the tumor oncogene KRAS and implicate that lncRNA-NUTF2P3-001 and miR-3923 can be applied as novel predictors and therapeutic targets for pancreatic cancer." (PMID 26755660, 2016). "Although miR-3923 is significantly decreased in pancreatic cancer tissue, data does not show statistical correlation between miR-3923 and KRAS expression." (PMID 26755660, 2016). "It is possible that a proportion of KRAS mutant pancreatic cancer do not release KRAS mutant cfDNA in the bloodstream, in which case the main limiting factor would be the biology of the tumor rather than the technology." (PMID 27705932, 2016). "Since KRAS is widely considered as promoter in pancreatic cancer tumorigenesis, thus we speculate that lncRNA-NUTF2P3-001 might be a functional lncRNA in pancreatic cancer by regulating KRAS expression." (PMID 26755660, 2016). "Here, (−)-epicatechin treatment reduced KRAS mutant pancreatic cancer cell viability but not that of normal cells, and it also reduced GTP-bound Ras protein levels, Akt phosphorylation, and NF-κB transcriptional activity." (PMID 26180580, 2015).